IL17A (interleukin 17A)
Diseases named in the same sentence as IL17A in open-access papers (continued):
Sharing a sentence is not in itself a finding about the gene and the disease.
COVID-19 (continued). "When stimulated with cytokines IL-12 and IL-18, impaired upregulation of IL-17A, TNFα, granzyme B and perforin was observed in the COVID-19 cohort, and a reduction in perforin was observed." (PMID 34050887, 2022). "Cytokines typical of Th2, Th9, Th17, and Tregs were either low or undetectable, although IL-6, IL-10, and IL-17A levels were higher in peptide-stimulated conditions compared with DMSO control conditions for convalescent COVID-19 participants." (PMID 35044955, 2022). "They observed a “key COVID-19 feature” shared by the moderate and severe disease groups, which they defined as the following inflammatory cytokines: IL-1α, IL-1β, IL-17A, IL-12 p70, and IFNα." (PMID 35774397, 2022). "Although no significant genome-wide association was detected in the Japanese GWAS, an integrated analysis with the international meta-GWAS identified for the first time the involvement of the IL17A/IL17F gene in the severity of COVID-19." (PMID 35264675, 2022). "On another note, levels of TNF-α and IL-17A were similarly more elevated in the mild-moderate and severe COVID-19 patients than in healthy controls." (PMID 35529862, 2022). "Hematologic cancer patients that showed highly networked and coordinated anti-SARS-CoV-2 antibody production, with central importance of IL-4, IL-5, IL-12A, IL-15, and IL-17A, presented only mild COVID-19." (PMID 36700209, 2022). "Our results show that surviving severe COVID-19 patients have lower circulating levels of IFNγ, IL-17A and sIL-4R than those with fatal outcomes." (PMID 36142255, 2022). "In a retrospective multiple-center study that enrolled 267 laboratory-confirmed coronavirus disease 2019 (COVID-19) cases, most patients had high plasma concentrations of IL-6 and IL-17A." (PMID 34602860, 2021). "Another interesting result is that the IL-17A tissue expression was slightly lower in rs2275913 than rs3819025 for the COVID-19 group and significantly higher in rs2275913 than rs3819025 for the H1N1 group." (PMID 33868301, 2021). "COVID-19 children had elevated levels of IFNγ, IL-2, TNFα, IL-1α, IFNα, IFNβ, IL-6, IL-17A and IL-10 in comparison to seropositive and/or control children." (PMID 33813138, 2021). "A study indicated the G allele of rs3819025 correlated with higher tissue expression of IL-17A in the COVID-19 cases." (PMID 34836309, 2021). "PIMS-TS children had significantly elevated levels of cytokines, IFNγ, IL-2, TNFα, IL-1α, IFNα, IFNβ, IL-6, IL-17A, GM-CSF, IL-10, IL-33 and IL-Ra in comparison to COVID-19, seropositive and control children." (PMID 33813138, 2021). "This study investigates the involvement of SNPs and tissue expression of IL-17A and the neutrophils recruitment in post-mortem lung samples from patients who died of severe forms of COVID-19 comparing to those who died by H1N1pdm09." (PMID 33868301, 2021). "Regarding cytokine-producing γδ T cells, compared with healthy subjects, less IFN-γ and more IL-17A (although the levels detected were always low) were released by γδ T cells from COVID-19 patients." (PMID 34071430, 2021). "In this study, the COVID-19 group showed IL-17A/IL-8 lower tissue expression and lower neutrophil score." (PMID 33868301, 2021). "Lymphocyte count was negatively associated with IFNγ, IL-2, TNFα, IL-1α, IFNβ, IL-6, IL-17A, IL-10, CXCL-10 and VEGF in children with PIMS-TS and COVID-19." (PMID 33813138, 2021). "CRP was positively associated with IFNγ, IL-2, TNFα IL-1α IFNβ IL-6 IL-17A IL-10, CXCL-10 and VEGF in children with PIMS-TS and COVID-19." (PMID 33813138, 2021). "Severe COVID-19 patients displayed reduced levels of IL-12p70, whereas the levels of IL-17A and IL-17F were lower in both mild and severe COVID-19 patients, compared to healthy donors." (PMID 33692788, 2021). "Although most of the cytokines examined herein were elevated in both diseases compared with healthy subjects (HC), active AOSD patients had significantly higher levels of IFN-γ, IL-17A, IL-18, and ferritin than COVID-19 patients." (PMID 34367188, 2021).
COVID-19 (continued). "When we probed cytokine (i.e. IL-12 and IL-18)-mediated MAIT cell activation, MAIT cells from COVID-19 patients showed an altered cytokine expression profile characterised by impaired upregulation of IL-17A, TNFα, granzyme B and perforin." (PMID 33546489, 2021). "The relevance of our findings is further supported by the fact that serum protein levels of GM-CSF and IL-17A were elevated in a cohort of patients with severe COVID-19." (PMID 33622974, 2021). "This study aims to evaluate the involvement of SNPs and tissue expression of IL-17A and the neutrophils recruitment in post-mortem lung samples from patients who died of severe forms of COVID-19 comparing to those who died by H1N1pdm09." (PMID 33868301, 2021). "IL-8 and IL-17A had significantly higher tissue expression in the H1N1 group than COVID-19 (p < 0.001, respectively)." (PMID 33868301, 2021). "Results are explorative but indicate that DPSCs can down-regulate the production of cytokines by activated PBMCs, e.g., TNFα, IFNγ, IL-10, and IL-17A, which are up-regulated in COVID-19 patients." (PMID 33634100, 2020). "Antigen-specific production of cytokines related to a Th17 response was also consistently detected; PBMC from COVID-19 ARDS patients produced significantly more IL-17A, IL-17F and IL-22 than HC." (PMID 32591408, 2020). "Longitudinal analysis of immune profiling of COVID-19 finds elevated plasma levels of IL-17A and IL-22 along with increased IL-17 secretion by CD4+ T cells in severe patients, indicative of promotive effects of Th17 cells in COVID-19 progression." (PMID 33584679, 2020). "On the adaptive immunity side, functional exhaustion was observed for Th17 lymphocytes producing IL17A in severe COVID-19 patients in comparison to mild forms and healthy subjects (p = 0.0004 and p = 0.002 respectively)." (PMID 33585507, 2020). "In the COVID-19+ group, postpartum hemorrhage (PPH) developed in 4 cases, associated with significantly reduced plasminogen, α2-plasmin inhibitor, and increased IL-8, IL-17A, IL-23 levels." (PMID 40303405, 2025). "Our findings align with previous studies indicating that inadequate IL-17A levels may impair immune responses and worsen COVID-19 outcomes." (PMID 40003732, 2025). "Moreover, it underscores the potential role of lesser-explored cytokines, such as IFN-α, IL-17A, and IL-23, in severe COVID-19." (PMID 39861879, 2025). "The elevated levels of IL-17A observed in our study among healthy and vaccinated individuals, compared to those with severe COVID-19 and recovered individuals, likely stem from its protective function against extracellular pathogens and its central role in innate immunity." (PMID 40003732, 2025). "The role of TNF-a and IL17a in COVID-19 severity is particularly intriguing." (PMID 39203987, 2024). "The primary objective of this study is to assess the predictive value and diagnostic potential of specific interleukins (IL-10, IL-17A, IL-1β, IL-6), chemokines (CXCL), and monocyte chemoattractant protein (MCP) in predicting severe COVID-19 outcomes and mortality." (PMID 39062105, 2024). "Moreover, the elevation of TNF-a and IL17a in severe COVID-19 cases invites further investigation into their potential as biomarkers for predicting disease progression and as targets for therapeutic intervention." (PMID 39203987, 2024). "This cytokine surge, particularly the roles of INF-g and IL17a, highlights the dual nature of the immune response in COVID-19, where protective mechanisms against the virus may inadvertently contribute to tissue damage and disease exacerbation." (PMID 39203987, 2024). "Except for IL-8 decreased in the second trimester after infected with SARS-CoV-2, IL-2, TNF-α, TNF-β, IFN-γ, IL-4, IL-5, IL-6, IL-10, IL-17A, IL-17F, IL-22, IL-1β and IL-12p70 didn't change in the three trimesters between healthy pregnancies and pregnant women with COVID-19." (PMID 39113896, 2024).
COVID-19 (continued). "Interestingly, the genetic variant chrX:15,584,534_ of the ACE2 gene correlated positively with CD40L, IL-1β, IL-2, IL-15, and IL-17A in COVID-19 patients." (PMID 38855114, 2024). "Interestingly, several cytokines such as IFN-γ, IFN-α, IL-1β, IL-2, IL-12p70, IL-17A and IL-33) decreased in moderate and severe COVID-19 patients compared to mild cases or healthy controls." (PMID 38855114, 2024). "This suggests that there is no clear association between IL-17A and this viral infection in the samples of patients with COVID-19 that we detected." (PMID 37047248, 2023). "Acute COVID-19 children had significantly elevated levels of cytokines, (Interferon (IFN)) IFNγ, Interleukins (IL)-2, TNFα, IL-1α, IL-1β, IFNα, IFNβ, IL-6, IL-12, IL-17A and Granulocyte-Colony Stimulating Factors (G-CSF) in comparison to convalescent COVID-19 and controls." (PMID 37013538, 2023). "Studies that evaluated biomarkers in relation to MIS-C indicated that MIS-C's inflammatory response differs from the cytokine storm in severe COVID-19, while sharing similarities with Kawasaki disease, albeit with discrepancies in T cell subsets, IL-17A, and artery damage biomarkers." (PMID 37954764, 2023). "First, we studied the profile of different soluble pro-inflammatory cytokines (GM-CSF, TNF-α, IFN-γ, IL-1β, IL-2, IL-6, IL-7, IL-10, IL-17A, IL-21) and chemokines mediating monocyte and neutrophil recruitment (IL8, CCL3), whose exacerbated production is associated with severe COVID-19." (PMID 36675231, 2023). "Although not statically significant, the polar charts show a signal towards the reduction in the production of pro-inflammatory cytokines, and specifically IL-1β, IL-2, IL-12, IL-13, IL-17A secreted by M2 macrophages of COVID-19 patients, after PD1 stimulation." (PMID 37153620, 2023). "Also, acute COVID-19 children had significantly elevated levels of cytokines, IFNγ, IL-2, TNFα, IFNβ, IL-6, IL-12, IL-17A and Granulocyte-Colony Stimulating Factors G-CSF in comparison to control children." (PMID 37013538, 2023). "In addition, the decreased number and impaired function of Treg cells, along with the elevated levels of IL-17A in COVID-19, have also been considered crucial pathological features of MG." (PMID 38384322, 2023). "To date, reports of IL-17A levels in COVID-19 patients with mild/moderate infection are scarce." (PMID 38283346, 2023). "In addition, some studies illustrate that patients infected with COVID-19 exhibited elevated plasma levels of IL-23 and IL-17, along with increased levels of IL-17A-producing CD4+ and CD8+ T lymphocytes." (PMID 38020100, 2023). "Th17 cells during COVID-19 are characterized by phenotype typical to tissue resident memory T cells also expressing the genes associated with cytolytic potential (SRGN, GZMB, and GNLY) and cytokine genes encoding IL-21, IL-17F, IL-17A, IFN-γ, and GM-CSF." (PMID 37626620, 2023). "Furthermore, the higher levels of IL-1β, IL6, IL-12p70, IL-17A, TNF-α, and IFN-γ are consistent with the inflammatory profile of COVID-19-associated lung injury." (PMID 38067158, 2023). "A review study observed that variants in cytokine genes such as IL-1β, IL1R1, IL1RN, IL-6, IL-17A, FCGR2A, and TNF may be associated with disease susceptibility and/or severity, cytokine storm, and/or COVID-19 complications like thrombosis." (PMID 37662953, 2023). "In patients with moderate disease, the core COVID-19 inflammatory cytokine signature with IL-1a, IL-1b, IL-17A, and IFN-α observed in the first 10 days from symptom onset declined steadily and the same happens with the innate cytokine IL-12, a key inducer of Th1 immune response, as well as IFN-γ." (PMID 35833134, 2022). "Moreover, CD4+ T cells, co-expressing CCR6 and IL-17A, were detected in lung tissues of patients with COVID-19." (PMID 36012146, 2022).
COVID-19 (continued). "While, both IL-6 and IL-10, as well as serum IL-17A, showed an increasing trend in severe COVID-19 patients after one week of hospitalization suggesting that, in more severe patients, the inflammatory status and the release of cytokines is a more prolonged phenomenon." (PMID 35893398, 2022). "So, as COVID-19 is also a respiratory disease, the production of IL-17A in the upper airway of individuals with SARS-Cov-2 infection can be crucial to elicit an immune response that limits disease severity, particularly by inducing specific-SIgA for COVID-19 as observed in the present study." (PMID 35686128, 2022). "Collectively, IL-19 as a component of the IL-23/IL-17 axis could strengthen the IL-17A-mediated immunopathological effect during severe COVID-19." (PMID 36163397, 2022). "To assess the general landscape of immune perturbation in different clinical settings of COVID-19, we contemporary measured the concentration in peripheral blood of six cytokines involved in the inflammation orchestrating: IL-6, IL-1β, IL-17A, TGF-β, TNF-α and IFN-γ." (PMID 35508575, 2022). "An increase in mortality of patients from IL-17 upregulation seems plausible, as upregulated IL-17A has been associated with acute respiratory distress syndrome (ARDS) and diseases that increase COVID-19 complications such as hypertension, diabetes, and obesity." (PMID 35572514, 2022). "COVID-19 patients with higher serum levels of IL-17A and GM-CSF had more severe clinical symptoms." (PMID 36034704, 2022). "Moreover, we observed that proinflammatory cytokines involved in lymphocyte and macrophage activation (IL-1β, IL-6, IL-16), Th2 (IL-4), and Th17 (IL-17A) responses were also increased in urine samples of COVID-19 patients." (PMID 36359444, 2022). "In the present study we evaluated the changes in serum IL-6, IL-10, and IL-17A levels and the cytometric lymphocyte profiles in 144 COVID-19 patients at admission and after one week of hospitalization, also in relation to steroid treatment before hospitalization." (PMID 35893398, 2022). "In the BAL fluid of patients with COVID-19, significantly increased and extremely high levels of the cytokines IL-1β, IL-1RA, IL-17A, TNF-α, and G-CSF and the chemokines CCL7, CXCL1, CXCL8, CXCL11, and CXCL12α were found in comparison with BAL fluid of patients with influenza." (PMID 34793331, 2022). "In the current study, we detected a statistically significant decrease in IL-17A levels in serum, PBMCs, and neutrophils of COVID-19 ICU patients compared with HCs, indicating an immunomodulatory effect of SARS-CoV-2 on IL-17 production by PBMCs and neutrophils." (PMID 36363785, 2022). "Circulating uT cells of COVID-19 patients produce less IFN-γ in the backdrop of more IL-17A, a pro-inflammatory and pro-fibrotic cytokine, whereas MAIT cells additionally showed an increased Granzyme B production, with a direct correlation between MAIT cytotoxic activity and severity of disease." (PMID 35757770, 2022). "MAIT cells isolated from COVID-19 patients expressed significantly higher levels of the pro-inflammatory cytokines TNFα and IL-17A, as well as of the cytolytic protein granzyme B compared to healthy controls ex vivo, while ex vivo expression of IFNγ and perforin was unchanged." (PMID 33546489, 2021). "The interrelationship of immune cells in COVID-19 was intrinsically identified, whereby T cells secreting IL-2, IL-4, and IL-17A were enriched among CD28+ and CD57− cells and cells secreting perforin/granzyme B/IFN-γ/tumor necrosis factor alpha (TNF-α)-expressed markers of terminal differentiation." (PMID 34488453, 2021). "However, the G allele (GG and GA) of rs3819025 was correlated with higher tissue expression of IL-17A in the COVID-19 group." (PMID 33868301, 2021). "Moreover, higher IL-17A in COVID-19 patients with severe disease supports the potential role for this cytokine in COVID-19-related acute respiratory distress syndrome." (PMID 33947753, 2021).
COVID-19 (continued). "In addition, several papers proposed use of therapies directed at Th17 cells and IL-17A signaling in treating COVID-19 patients." (PMID 33603759, 2021). "To test whether GM-CSF and IL-17A correlate with the severity of COVID-19, we first measured these two cytokines in the serum of patients with COVID-19 and of healthy blood donors and observed increased GM-CSF concentration in the patients." (PMID 33622974, 2021). "For instance, patient DRASTIC-063 displayed higher IFN-2, IL-10, IL-12p70 and IL-17A in ETA (d8) than other COVID-19 respiratory samples, while the plasma (d7) level of IFN-2 was also higher, DRASTIC-063 had higher plasma level of IL-18 but not IL-10, IL-12p70 or IL-17A." (PMID 34462740, 2021). "Furthermore, it is well documented that IL-17A was significantly elevated in both moderate and severe cases of COVID-19 compared to the controls." (PMID 34696395, 2021). "Variants in cytokine genes such as IL1B, IL1R1, IL1RN, IL6, IL17A, FCGR2A, and TNF could be related to disease susceptibility and cytokine storm, and/or COVID-19 complications (e.g., venous thrombosis)." (PMID 33868239, 2021). "To conclude, the further use biobank method seems suitable for investigating COVID-19 cytokine-related research questions, but variation on IL-17A, IL-6 and IL-12p70 levels might have been introduced by the applied delay in processing." (PMID 34289718, 2021). "For these reasons, it could be possible that, in COVID-19 patients, IL-17A could potentially promote a pro-thrombotic state in the vascular system." (PMID 33353549, 2020). "Taking these data together, we can hypothesize that the concomitant increase of IL-12p70 with IL-17A observed in the COVID-19 group with SIgA could be an important feature in order to promote an efficient stimulation of the immune response in the airway’s mucosa, leading to SIgA production." (PMID 35686128, 2022). "IL-17A therefore, may be a key player in the COVID-19 cytokine storm." (PMID 35250672, 2022). "However, this association between the salivary levels of IL-12p70 and IL-17A, seemingly, is not the unique factor able to induce the SIgA production in COVID-19 patients, since the COVID-19 group without SIgA did also present the same correlation." (PMID 35686128, 2022). "Whereas previous studies did not demonstrate significant benefit of anti-IL-17A therapy for severe COVID-19, our data suggest that such therapy could be a rational choice for mild-to-moderate disease, considering the generally high safety profile of IL-17A blockers." (PMID 36001576, 2022). "The overactivation of IL-17-producing Th17 cells may occur in patients with COVID-19 and the use of monoclonal antibodies against IL-17A (such as secukinumab and Ixekizumab) has been discussed as an efficient treatment to prevent organ injury caused by the immune response to COVID-19." (PMID 34440765, 2021). "Possibly, the higher concentrations of IFN-γ and IL-17A in the serum of pediatric patients with COVID-19 reflected increased expression by cells in the respiratory tract, and these local cytokines may have protected the patients from progressive respiratory disease." (PMID 32958614, 2020). "However, in individuals where this response is excessive, it may turn detrimental to the host and become a component of the pathological inflammatory process in COVID-19, where the IL-17A bias of mucosal MAIT cells may be important." (PMID 32989174, 2020). "Significantly higher expression of IFN-γ (p = 0.0153), IL-6 (p < 0.0001), IL-10 (p < 0.0001), IL-17A (p = 0.0310), and TNF-α (p = 0.0034) was observed in COVID-19 patients compared to uninfected participants." (PMID 42023234, 2026). "In patients with the PAP phase of COVID-19, an increase in proinflammatory cytokines, namely, IFN-α, TNF-α, G-CSF, IL17A, IL-6, IL1-β, and IL-13, has been confirmed in a number of studies." (PMID 40002929, 2025).